IL10 (interleukin 10)
Diseases named in the same sentence as IL10 in open-access papers (continued):
Sharing a sentence is not in itself a finding about the gene and the disease.
asthma (continued). "Interleukin-10 (IL-10) has been associated with wheezing and asthma in children and the genetic variation of the IL-10 cytokine production may be linked to post-bronchiolitis lung function." (PMID 26473365, 2015). "The IL-10 -1082 G/A polymorphism confers susceptibility to asthma in East Asians and in adults." (PMID 23335974, 2013). "Gene polymorphism in IL-10 has been reported to play an important role in the onset of asthma." (PMID 23717481, 2013). "The increased IL-10 and decreased IL-12 in asthma children indicates the loss of balance in Th1/Th2 cells, confirming the important role of Th1/Th2 balance in the mechanism of asthma pathogenesis." (PMID 23717481, 2013). "In the current study, we present the results of a comprehensive search of literature and meta-analysis to explore whether the IL-10 -1082 G/A, -819 C/T, -592 C/A polymorphisms, and their haplotypes contribute to asthma susceptibility." (PMID 23335974, 2013). "However, the meta-analysis of the five studies in H-W equilibrium produced results for the relation between the IL-10 -1082 G allele and asthma (OR = 0.71, 95% CI = 0.60–0.83, p<0.0001)." (PMID 23335974, 2013). "IL-10 is produced by macrophages and by a subset of regulatory T cells (Tregs) and exerts its effects by inhibiting the synthesis of inflammatory cytokines (including asthma-associated cytokines such as TNF-α and IL-5) and gene presentation." (PMID 23781124, 2013). "Meta-analysis of association between the IL-10 -592 C/A polymorphism and asthma." (PMID 23335974, 2013). "The aim of this study was to explore whether the interleukin (IL)-10 polymorphisms and their haplotypes contribute to asthma susceptibility." (PMID 23335974, 2013). "Meta-analysis of association between the IL-10 -1082 G/A polymorphism and asthma." (PMID 23335974, 2013). "However, meta-analysis of the five studies in Hardy-Weinburg equilibrium produced the relationship between the IL-10 -1082 G allele and asthma (OR = 0.71, 95% CI = 0.60–0.83, p<0.0001)." (PMID 23335974, 2013). "Most of the asthmatic children in our study had asthma which was induced by an airway viral infection, which could be associated with the high expression of IL-10." (PMID 23717481, 2013). "Meta-analysis of association between the IL-10 -819 C/T polymorphism and asthma." (PMID 23335974, 2013). "Furthermore, stratification by age indicated an association between the IL-10 -1082 G allele and asthma in adults and mixed groups (OR = 0.77, 95% CI = 0.62–0.96, p = 0.02; OR = 0.67, 95% CI = 0.49–0.92, p = 0.01)." (PMID 23335974, 2013). "Deregulation of IL-10 was associated with various diseases, such as cancer, rheumatoid arthritis, systemic lupus erythematosus, asthma, infectious disorders, and so forth, where both overexpression and IL-10 deficiency were shown to have a pathophysiological significance." (PMID 23062006, 2012). "Nevertheless, the extent of IL-10 synthesis may be indicative of the type of immune response associated with effective asthma treatment." (PMID 21386995, 2011). "The low IL10-producing haplotype was associated with asthma in the same population (SLSJ)." (PMID 19852851, 2009). "The effect of the IL10 variant on asthma seemed dependent on the VDR variant." (PMID 19852851, 2009). "Five SNPs in the IL10 gene, three located in the promoter (rs1800872, rs1800871, rs1800896), one in intron 1 (rs3024490), and the other located in the 3' region (rs4844553) were significantly associated with asthma." (PMID 19852851, 2009). "New "counterregulatory" models of asthma pathogenesis suggest that dysfunction of IL-10–related regulatory mechanisms might underlie the development of asthma." (PMID 18315837, 2008). "Polymorphisms of the IL-10 promoter have been associated with risk of asthma and ABPA." (PMID 16503977, 2006).
asthma (continued). "Therefore, in this study, we conducted a systematic review and meta‐analysis to combine all available published data to investigate whether IL10 rs1800896 polymorphism contributes to susceptibility to asthma." (PMID 37937689, 2023). "Notably, recent animal studies have reported that vitamin D deficiency in utero and in early life leads to elevated Th2 and reduced interleukin (IL)-10-secreting Treg cells, thereby potentially increasing the risk of asthma, which has been considered a Th2-mediated disease." (PMID 36143913, 2022). "Furthermore, we have found links between AAPs and DNA methylation of specific CpG sites of IL10 and FoxP3 genes in children with asthma and more recently that AAP exposure was associated with altered methylation of CpG sites for IFNγ, IL4, IL10, and FoxP3 genes." (PMID 35287715, 2022). "However, IL-10 was demonstrated to be dispensable for its inhibition of experimental asthma, although increased Il10 mRNA could be detected in nasal associated lymphoid tissue (NALT) harvested from mice 14 days after Protollin administration." (PMID 32983168, 2020). "Notably, the phenotype of vitamin D deficiency in severe asthma, and in particular treatment refractory asthma is associated with a neutrophilic profile, an enhanced pro-inflammatory Th17 phenotype and impaired induction of anti-inflammatory IL-10." (PMID 30690074, 2019). "In addition, asthma was associated with higher differentially methylated regions of Foxp3 and IL10." (PMID 29317916, 2018). "Indeed, impaired IL-10 responses have been associated with HRV-induced asthma exacerbations." (PMID 28552993, 2017). "It is speculated that the level of IL-10 in asthma onset is correlated with the cause of diseases." (PMID 23717481, 2013). "Thus, the accumulation of MDSCs may be the cause of IL-10 up-regulation and IL-12 down-regulation, thereby affecting asthma onset and development." (PMID 23717481, 2013). "Furthermore, stratification by age indicated an association between the IL-10 -1082 G allele and asthma in adults and mixed groups (OR = 0.77, 95% CI = 0.62–0.96, p = 0.02; OR = 0.67, 95% CI = 0.49–0.92, p = 0.01), but not in Child (OR = 1.07, 95% CI = 0.64–1.76, p = 0.80)." (PMID 23335974, 2013). "CD69 binding to Gal-1 on DCs induces IL-10+ T cells with anti-inflammatory properties, while its interaction with Myl9/12 recruits activated T cells to inflamed lungs in asthma." (PMID 40574085, 2025). "IL-10 is an immunosuppressive cytokine, and clinical studies have revealed that serum IL-10 level can reflect the severity of asthma." (PMID 39820222, 2025). "In a mouse model of asthma induced by ovalbumin sensitization, intratracheal administration of IL-10 significantly suppressed the infiltration of eosinophils and neutrophils as well as the development of airway hyperresponsiveness." (PMID 41312367, 2025). "Significant differences were observed in IL-6, IL-10, IL-13, 25-(OH) D3 levels, and leptin among children with asthma combined with obesity/overweight and those with asthma or obesity/overweight alone." (PMID 40083433, 2025). "In conclusion, there were significant differences in IL-6, IL-10, IL-13, 25-(OH) D3 levels, and leptin levels among children with asthma combined with obesity/overweight and those with asthma or obesity/overweight alone." (PMID 40083433, 2025). "IL-13 is a key mediator in allergic inflammation, particularly in respiratory allergy and asthma, while IL-10 plays a role in immune tolerance and anti-inflammatory responses." (PMID 40944184, 2025). "Dynamics of the IL-10 level in asthma and COPD patients vaccinated against influenza and healthy volunteers (reference value: Less than 20 pg/mL)." (PMID 39937802, 2025). "Very recently it has been described that IL-9 induction was restrained by IFN-γ/STAT1 and IL-10, pointing to a new role of this pathway in the modulation of asthma disease." (PMID 40650018, 2025).
asthma (continued). "This study used an asthma animal model and macrophage depletion and demonstrated a significant exacerbation of asthma symptoms upon macrophage removal, coupled with a marked reduction in IL-10+ B-cell expression." (PMID 40342727, 2025). "This response is impaired in asthma: CD4+ T cells isolated from the PBMCs of patients with asthma have impaired production of IL-10 in response to CD3/CD46 stimulation compared with controls." (PMID 40309766, 2025). "MSC-EVs have demonstrated good efficacy in ALI, lung transplantation, and asthma, with the anti-inflammatory effects being mediated by IL-10." (PMID 41312367, 2025). "A study on viral infections leading to childhood asthma also confirmed the correlation between decreased IL-10 levels and asthma incidence." (PMID 41312367, 2025). "As a result, IL‐10 levels increase, suppressing excessive inflammation in the body and controlling asthma symptoms." (PMID 40611442, 2025). "This suggests that the immunomodulatory effects of MSCs synergize with the immunoregulatory effects of IL-35 and IL-10 to jointly regulate the progression of asthma inflammation." (PMID 41309530, 2025). "In allergic disorders such as atopic dermatitis and asthma, overexpression of IL-10 has been considered a counter-regulatory response to limit inflammation." (PMID 40630332, 2025). "Purpose of this study is to investigate dynamics of CRP, serum cytokines (IL-2, IL-6, IL-10, IL-17) in patients with asthma and COPD, as well as to perform a correlation analysis with the clinical manifestations of the diseases within a year after vaccination." (PMID 39937802, 2025). "IMs are another source of IL-10, and as with the IL-10 secreted by AMs, they are also important in alleviating asthma development." (PMID 39861052, 2025). "Asthma: Blimp-1 has previously been found to be important for IL-10 production in ILC2s in airway inflammation models." (PMID 40002370, 2025). "IL-10 is a regulatory cytokine known for its therapeutic role in treating inflammatory conditions such as asthma and in modulating vascular smooth muscle cells 43-45." (PMID 40303299, 2025). "Further analysis revealed that the macrophages interacting with IL-10+ B cells in the asthma microenvironment were of the M2 subtype." (PMID 40342727, 2025). "While asthmatic AMs produce a greater number of anti-inflammatory IL-10, which corticosteroids can amplify, asthmatic AMs can also produce pro-inflammatory effects that drive the progression of asthma." (PMID 39861052, 2025). "Prior studies indicate that IL-10 inhibits the onset of asthma through decreased Th2 cytokine production." (PMID 40083432, 2025). "Our study conducted on an asthma mouse model revealed that the lung microenvironment fosters the generation of IL-10+ B cells by M2 macrophages, improving the disease." (PMID 40342727, 2025). "Lipopolysaccharide (LPS) has been found to induce histone H3 acetylation in the promoter region of IL-10 gene in mDCs, and montelukast, an asthma therapeutic drug, can further enhance this process." (PMID 41246337, 2025). "In pathological conditions, such as asthma, IL-10 production decreases, indicating a possible relationship between its deficiency and asthmatic inflammation." (PMID 38774212, 2024). "Bregs express the anti-inflammatory cytokine IL-10, which is thought to have a positive effect on asthma pathophysiology by suppressing the IgE-mediated allergic cascade and decreasing airway inflammation." (PMID 38172451, 2024). "The number of IL-5-, IL-10-, and IL-13-producing peripheral blood mononuclear cells (PBMCs) derived from all children at the asthma camp significantly (p < 0.05) decreased in the water aerosol group." (PMID 38398384, 2024). "The literature does, however, provide conflicting information about cytokine levels of IL-6 and IL-10 in AR, in adolescents with AR and asthma." (PMID 38398030, 2024). "The reduced levels of IL-10 in both asthma and obesity indicate the common mechanistic link between these both conditions." (PMID 39902293, 2024).
asthma (continued). "Parasite infection in allergic mice models for asthma reveals protection from lung inflammation and airway hyperresponsiveness through IL-10-producing Bregs." (PMID 38172451, 2024). "Our findings indicate that several cytokines, including IL-5, IL-17A, IL-22, IL-33, TNF-α, leptin, and IL-10 were independently influenced by asthma and obesity." (PMID 39902293, 2024). "IL-10 is also thought to have a positive effect on asthma pathophysiology by suppressing the IgE-mediated allergic cascade and decreasing airway inflammation." (PMID 38172451, 2024). "ELISA was used to measure concentrations of cytokines (IL-1β, IL-18, IL-17A, and IL-10) in serum samples collected from asthma patients and healthy individuals." (PMID 38849380, 2024). "Several studies showed that IL-10 expression has a positive effect on asthma pathophysiology and that higher Breg numbers are characteristic of allergen tolerance." (PMID 38172451, 2024). "This highlights IL-10 as an important candidate in future mechanistic studies investigating the role of vitamin D in asthma." (PMID 38751303, 2024). "Nevertheless, CPC and MP treatments lower the synthesis of these pro-inflammatory cytokines and increase the synthesis of anti-inflammatory cytokines IL-10 (~8%) and IL-4 (~3%) compared to asthma-induced groups." (PMID 39000141, 2024). "The concentrations of IL-10, IL-13, and IL-17 A in the asthma group were significantly lower than those in the control group (IL-10: P = 0.043; IL-13: P = 0.014; IL-17 A: P = 0.026)." (PMID 38218943, 2024). "In asthma, IL-10 can negatively regulate the inflammatory response mediated by Th2 and Th17 and can alleviate the severity of neutrophilic asthma." (PMID 38218943, 2024). "The cytokine IL‐10 has a unique function in safeguarding against allergic airway inflammation in individuals with asthma." (PMID 38888451, 2024). "The presence of IL‐10 plays a pivotal role in suppressing asthma symptoms by modulating the activity of APC and attenuating IgE production." (PMID 38888451, 2024). "Many studies have confirmed that IL-10 has anti-inflammatory benefits that alleviate the symptoms of asthma because of the increased CD8 T cell population and the reduced conversion of IgE." (PMID 38674852, 2024). "Although eosinophils are an important player in the pathogenesis of asthma exacerbation, they secrete IL-10, suggesting a subtype of eosinophils as a regulator at the inflamed site." (PMID 38540778, 2024). "SCFAs increase the expression of transcription factor FOXP3 by inhibiting histone deacetylation, supporting the expansion of Tregs and increasing the production of IL‐10, which in turn interacts with the host immune and participates in asthma." (PMID 38687096, 2024). "Noteworthy, the induction of certain anti-inflammatory circuits in H. pylori infection, such as the promotion of interleukin 10 (IL-10)-producing regulatory T cells (Tregs), benefits the host by counteracting the development of atopic diseases like asthma." (PMID 38318189, 2024). "Tolerogenic vaccination with antigen-loaded tolDCs engineered to express IL-10 suppressed disease in mouse models of T1D and asthma, and antigen-loaded tolDCs cultured in presence of IL-10 reduced disease in EAE." (PMID 39759532, 2024). "To determine the protective effect of the treatment against the physical manifestations of asthma, we evaluated the effect of IL10-AMNPs on the lung function following HDM exposure." (PMID 37275919, 2023). "IL-4, IL-17, IFN-γ, and IL-10 are the representative secretion factors of Th1, Th2, Th17, and Treg cells in asthma." (PMID 36636604, 2023). "Human studies are needed to evaluate the relevance of KLRG1+ and KLRG1-ILC2 subsets and IL-10 production in asthma pathophysiology and sex disparity." (PMID 37947634, 2023). "Low expression of IL‐10 can contribute to the development of asthma, whereas high levels of IL‐10 can protect against airway inflammation." (PMID 37937689, 2023).
asthma (continued). "This further suggests a defective IL-10 system in asthma and calls for therapeutic methods that can raise IL-10 levels to healthy levels." (PMID 37947634, 2023). "Similar to previous findings, children with moderate and steroid-resistant asthma have been found to have significantly diminished levels of IL-10 in their airway lavages and peripheral blood mononuclear cells (PBMCs) when compared to non-asthmatic controls." (PMID 37947634, 2023). "Disorders of intestinal flora disorders can trigger various systemic chronic inflammatory conditions, and IL-4, IFN-γ, IL-17, and IL-10 are potentially correlated with the pathogenesis of asthma." (PMID 36636604, 2023). "Glucocorticoids and statins reduce asthma inflammation by promoting IL-10 production by inhibiting autophagy in macrophages." (PMID 37090692, 2023). "Some studies have shown that the blood IL-10 content of asthma patients is significantly reduced, suggesting that IL-10 content is correlated with the occurrence and aggravation of airway inflammation." (PMID 38077793, 2023). "Compared to non-asthmatics, there are low levels of IL-10 in the bronchoalveolar lavage fluid (BALF) of patients with asthma and low production of IL-10 from alveolar macrophages." (PMID 38093354, 2023). "Inducible Tregs producing IL-10 are reduced in the blood of unstable severe asthmatic patients compared with patients with mild and severe stable asthma." (PMID 38106504, 2023). "In keeping with this, IL-17 and IL-10 were shown to be increased in the older asthma patients compared to the younger." (PMID 36291665, 2022). "The association of tissue helminth infections with peripheral blood eosinophilia, the presence of cytokines including IL-10 and IL-4, and elevated IgE levels are hypothetical pieces of evidence for the relationship between HI and asthma." (PMID 36250067, 2022). "Another clinical research showed that Tregs induced by glucocorticoids expressed and generated more IL-10 to suppress the process of inflammation and thus alleviate lung injury, which explained the effectiveness of glucocorticoids in standard asthma therapy." (PMID 35812246, 2022). "Some of the beneficial effects of vitamin D on asthma include its effect on Treg cells and IL-10, which also suppresses Th2 responses." (PMID 36143913, 2022). "It is an important result, once levels of IL-2 (6D), IFN-ɣ (6E), and IL-10 (6F) in serum of asthma mice were higher than those found in the control group." (PMID 36685604, 2022). "We previously reported that E. granulosus s.s. infection alleviated asthma symptoms by enhancing interleukin 10 (IL-10) and downregulating IL-5 and IL-17A." (PMID 36289514, 2022). "In clinical trials, the levels of IL-12, IFN-γ, and Th1 percentage decreased in pneumonia and asthma children's peripheral blood, while the levels of IL-4 and IL-10 and the percentages MDSCs and Th17 increased." (PMID 36045657, 2022). "IL-12, IFN-γ, and Th1 cells decreased, while L-4, IL-10, MDSCs, and Th17 cell increased in peripheral blood of patients with asthma and pneumonia." (PMID 36045657, 2022). "Treg IL-10 cytokine production was elevated to near normal levels, and the production of chemoattractant biomarkers involved in the inflammation of airways of asthma mice were inhibited." (PMID 36115955, 2022). "In this study, the percentage of MDSCs, and the levels of IL-4 and IL-10 increased in asthma and pneumonia group, but the levels of IL-12 and IFN-γ reduced." (PMID 36045657, 2022). "To determine the relationship between PRB1 and type 2‐high asthma further, we detected the levels of IL‐2, IL‐4, IL‐5, IL‐6, IL‐10, IL‐13, IL‐17, and INF‐γ in the induced sputum supernatant." (PMID 35344278, 2022). "In alveolar macrophages from asthma patients inhibition of autophagy by 3-MA induces the secretion of the anti-inflammatory cytokine IL-10." (PMID 35608088, 2022).